TRAF6 (TNF receptor associated factor 6)
Diseases named in the same sentence as TRAF6 in open-access papers (continued):
Sharing a sentence is not in itself a finding about the gene and the disease.
lung carcinoma (continued). "We report that CD44 cleavage in A549 lung cancer cells and other cells is promoted by transforming growth factor-beta (TGFβ) in a manner that is dependent on ubiquitin ligase tumor necrosis factor receptor-associated factor 4 or 6 (TRAF4 or TRAF6, respectively)." (PMID 33804427, 2021). "The miR-146a rs2910164 C>G polymorphism might contribute to genetic susceptibility to lung cancer in Chinese nonsmoking females through affecting miR-146a expression and secondary structure, as well as directly influencing the target gene TRAF6." (PMID 27911870, 2017). "The combined treatment of Rosa canina extract and cisplatin significantly inhibited lung cancer cell proliferation by downregulating PARP-1 and the TLR2/MyD88/TRAF6/NF-κB signaling pathway, as well as the PI3K/Akt/mTOR pathway." (PMID 40022036, 2025). "In lung cancer, USP4 was identified as a negative regulator of TNFα-mediated lung cancer cell migration through deubiquitination of TRAF2 and TRAF6." (PMID 38802791, 2024). "In this study, we found that targeting USP24 by the specific USP24 inhibitors, USP24-i and its analogues, dramatically activated autophagy in the interphase and mitotic periods of lung cancer cells by inhibiting E2F4 and TRAF6, respectively." (PMID 38491202, 2024). "Given the molecular mechanism by which ARRB2 inhibited the TRAF6-related signaling axis for the activation of NF-κB and autophagy induction, we verified the functional role of ARRB2 in lung cancer progression." (PMID 37443143, 2023). "SET domain bifurcated histone lysine methyltransferase 1 (SETDB1) methylates Akt and functions as a scaffold to recruit JMJD2A, which then binds TRAF6 and Skp2-SCF to the Akt complex, thereby promoting tumor development in lung cancer." (PMID 35874839, 2022). "Thus, miR-146a rs2910164 polymorphism may influence susceptibility to lung cancer in Chinese nonsmoking females through targeting TRAF6." (PMID 27911870, 2017). "TRAF6 integrates the NF-κB and RAS pathways to stimulate the progression of lung cancer." (PMID 36366411, 2022). "However, the crosstalk between TRAF6 and TXNIP in non‐small cell lung cancer (NSCLC) is currently unclear." (PMID 31578830, 2020). "Although not listed in TCGA, TRAF6 amplification is recognized as one of the most frequent genomic alterations in human lung cancer (9.2%, 24/261) and OSCC (10%, 2/20)." (PMID 30294322, 2018). "Moreover, a study by Starczynowski and colleagues showed that TRAF6 exhibited concomitant mRNA overexpression and gene amplification in RAS-driven lung cancers." (PMID 29202848, 2017). "In addition, TRAF6, an important molecule in the TLR/IL-1R pathway, is overexpressed in lung cancer tissues and related to a chemoresistance." (PMID 27248820, 2016). "To test whether this was also true in lung cancer cells, we generated H460 for Dox inducible expression of Clusterin (designated H460-tet-CLU) and found that CLU expression effectively inhibited recruitment of TRAF6 by TGFBR1." (PMID 33052230, 2020). "Additionally, activation of TLR4 and TLR3 stimulated autophagy induction in lung cancer cells and induced enhancements of cytokine productions, such as IL-6, CCL2/MCP-1, CCL20/MIP-3α, VEGFA, and MMP2, by encouraging TRAF6 ubiquitination, thereby led to increases of cell migration and invasion." (PMID 31620128, 2019). "However, the precise role of TRAF6 protein in lung cancer has not been extensively investigated." (PMID 26582220, 2015).
breast carcinoma (48 papers, 2010 to 2025). "Overall, we tentatively conclude that TRAF6 is associated with breast cancer cell behaviour in vitro, tumour burden and metastasis in mice, and bone metastasis and survival rate in breast cancer patients." (PMID 36944688, 2023). "Our research identified 7 human studies that examined the association of TRAF2 (1 study), TRAF4 (3 studies), and TRAF6 (3 studies) with survival rate in breast cancer patients (719 patients)." (PMID 36944688, 2023). "While little is known regarding the association of TRAF6 in breast cancer, it was found over-expressed in triple negative BC and it expression correlates with metastatic outcome." (PMID 33670375, 2021). "Furthermore, in oral and breast cancers, the underlying molecular mechanism of TRAF6 is the promotion of AKT ubiquitination and phosphorylation." (PMID 32724313, 2020). "While the role of TRAF6 in human breast cancer is not yet fully understood, some studies suggest its potential oncogenic activity." (PMID 38169510, 2024). "TRAF6 exhibits high expression levels in breast cancer, particularly in cases with bone and brain metastases, and its expression is inversely correlated with breast cancer prognosis." (PMID 38825674, 2024). "In the following sections, we provide a comprehensive overview of the current understanding regarding the role of TRAF6 in gastrointestinal neoplasms, urogenital malignancies, myoid cancers, breast cancer, and other cancer categories." (PMID 38169510, 2024). "Strategies aimed at reducing TRAF6 expression have been shown to inhibit the proliferation and metastasis of breast cancer cells." (PMID 38825674, 2024). "As manifested in the immunohistochemistry, TRAF6 was detected to present overexpression in breast cancer." (PMID 37746908, 2023). "A review of non-pooled studies confirmed that high expression of TRAF6 was detected in patient biopsies from both human breast carcinoma and lymph node metastasis." (PMID 36944688, 2023). "Both PRMT5 and TRAF6 are frequently overexpressed in various types of human cancers, including breast cancer, colorectal cancer, gastric cancer." (PMID 37173967, 2023). "Breast cancer patients with gain or amplification of TRAF6 (n = 213) exhibited significantly lower overall survival rate compared to patients that are diploid (n = 1738) (p < 0.05)." (PMID 36944688, 2023). "Based on qRT‐PCR, the TRAF6 mRNA level was verified to be higher in breast cancer than in benign tumors." (PMID 37746908, 2023). "Our study provides preliminary evidence to show that a combination of PRMT5 and TRAF6 inhibitors achieves a better anti-proliferative effect in breast cancer cells." (PMID 37173967, 2023). "In contrast, TNF receptor-associated factor 6 (TRAF6), another E3 ubiquitin ligase, promotes K63-linked polyubiquitination of PRMT5, enhancing its methyltransferase activity on histone H4R3 and breast cancer cell proliferation." (PMID 37928266, 2023). "Other groups have reported that RANK signaling is also involved in breast cancer development by mechanisms distinct from ours.68,69) Moreover, we demonstrated that TRAF6-mediated TLR4 signaling also induces JAG1 expression in macrophages." (PMID 33840674, 2021). "A previous study demonstrated that miR-146b inhibited the NF-ᴋB-IL-6-STAT3 pathway by targeting TRAF6 in breast cancer." (PMID 34369236, 2021). "In breast cancer cells, TRAF6 overexpression correlated with increased HIF-1α signaling and metastasis." (PMID 33142239, 2020). "Studies showed that TRAF6 is overexpressed in various types of tumor, including colon, gastric, breast carcinomas and melanoma." (PMID 32905356, 2020). "A total of 193 cancers (59.6%) are identified to have high TRAF6 expression, including uterine fibroids, glioma, pancreatic cancer, breast cancer, glioblastoma multiforme (GBM), colorectal cancer, and squamous cell carcinoma of head and neck (SCCHN)." (PMID 33294443, 2020).
breast carcinoma (continued). "More recently, TRAF6 was also implicated in cancer signalling, by regulating epithelial to mesenchymal transition (EMT) in colon cancer, DNA damage in breast cancer backgrounds, and involvement in autophagy responses." (PMID 32344511, 2020). "Further experiments would be required to elucidate the precise roles of TRAF6 in normal mammary gland and breast cancer development." (PMID 31396572, 2019). "Consistent with the frequent amplification of TRAF6 in human cancers, TRAF6 is overexpressed in many human cancers such as breast cancer, HCC, colon cancer, esophageal cancer, and melanoma." (PMID 30294322, 2018). "In Rezaeian's study, the hypoxia-responsive TRAF6 overexpression promotes breast cancer progression and metastasis to lung and spinal bone, and targeting of TRAF6 reduces breast cancer metastasis, opening up opportunities for therapeutic intervention." (PMID 28969036, 2017). "Overexpression of miR-146a/b results in downregulation of IRAK1 and TRAF6 and subsequently inhibits NF-κB activation, leading to tumor suppression in breast cancer cells." (PMID 26697527, 2015). "In summary, TRAF6 appears to play a pivotal role as a molecular intermediary in breast cancer." (PMID 38169510, 2024). "Whilst these findings indicate that TRAF6 is an important regulator of breast cancer tumorigenesis and metastasis, accumulating evidence from studies in advanced breast cancer patients suggests that the expression of TRAF2 and 4 is associated with poor survival rates." (PMID 36944688, 2023). "Since TNBC is known to possess a high rate of invasiveness and recurrence, we hypothesized that TRAF6 could have the potential to promote breast cancer progression." (PMID 37746908, 2023). "TRAF6 has emerged as a key regulator of breast cancer (BCa)." (PMID 36944688, 2023). "Our meta-analysis of pooled in vitro, in vivo, and human studies, coupled together with bioinformatics validation confirm that TRAF6 inhibition may be of value in the management of multiple aspects of advanced breast cancer." (PMID 36944688, 2023). "mean difference − 4.15, 95% CI − 6.06, − 2.24, Z score 4.25 (P < 0.0001)) is associated with significant reduction in tumour weight and volume in female rodents bearing the human triple-negative MDA-MB-231 (TRAF2, TRAF4 and TRAF6) and mouse 4T1 (TRAF6) breast cancer cells." (PMID 36944688, 2023). "Furthermore, TRAF6 and TRAF2 have also been found to be enriched in an additional 15 pro-inflammatory and immuno-modulatory pathways and processes implicated in breast cancer tumorigenesis and metastasis." (PMID 36944688, 2023). "Therefore, TRAF6 is likely to be involved in the physiological development of the mammary gland and, at the same time, contribute to breast cancer development." (PMID 33840674, 2021). "This combination might be beneficial in breast cancer metastasized in bones because TRAF6 is overexpressed on osteotropic breast cancer cells and even greater levels of this protein are detected in patients with bone metastasis." (PMID 33802861, 2021). "Furthermore, analysis of publicly released datasets for HIF-1β ChIP-seq identified a specific binding site in the promoter region of TRAF6 in T47D breast cancer cells." (PMID 32344511, 2020). "Analysis of members of the TLR4 signal transduction cascade revealed comparable expression levels of Myd88 and TRAF6 in MDA-MB-435-Hyg breast cancer cells and M13MDA435 hybrid cells, whereas in M13SV1-EGFP-Neo breast epithelial cells the expression levels of these proteins were much lower." (PMID 26863029, 2016). "In terms of the relevance of IL-1β to breast cancer cell aggressiveness, breast cancer metastasis suppressor 1 has been shown to up-regulate miR-146, which targets key IL-1 receptor signaling molecules, including IRAK1 and TRAF6, and suppresses the metastasis of breast cancer cells." (PMID 27609180, 2016).
breast carcinoma (continued). "Moreover, TLR4 and TLR9 as well as TRIF, Myd88 and TRAF6 expression levels of MDA-MB-435-Hyg breast cancer cells were comparable to M13MDA435-1 and -3 hybrid cells." (PMID 27187369, 2016). "Interestingly, LPS treatment did not result in an increased nuclear translocation of NF-κB in MDA-MB-435-Hyg breast cancer cells despite Myd88 and TRAF6 expression." (PMID 26863029, 2016). "TRAF6, the innate immune molecule down-regulated by miR-146a in breast cancer, has also been shown to negatively regulate VEGF in epithelial cells, leading to the question of whether the miR-146a regulatory pathway may result in increased VEGF signaling and angiogenesis." (PMID 23335942, 2012). "Hsa-miR-125b-5p regulates cancer cell growth and proliferation by suppressing the TRAF6/MAPK/NF-κB pathway in osteoarthritic chondrocytes and targeting MMP1 in breast cancer." (PMID 39684278, 2024). "Lastly, we found that, compared to the single agent, co-treatment of TRAF6 and PRMT5 inhibitors significantly decreased cell viability in breast cancer cells, which is in part achieved by enhancing cell apoptosis." (PMID 37173967, 2023). "To gain more insight into the mechanism(s) by which TRAF6, as well as TRAF2 and 4, influence the progression and metastasis of breast cancer, we conducted a KEGG pathway enrichment analysis." (PMID 36944688, 2023). "Previously reported studies have shown that TRAF6 is overexpressed in breast cancer, especially in TNBC patients who produce higher expression than those who carry HR+ and HER2+ breast cancer." (PMID 37746908, 2023). "To investigate the biological function of TRAF6-mediated PRMT5 ubiquitination, we reintroduced PRMT5-WT, PRMT5-3A, or PRMT5-6KR into PRMT5-depleted breast cancer cells." (PMID 37173967, 2023). "TRAF6 is the most studied member of the TRAF family, and a number of studies have demonstrated its involvement in breast cancer, inflammation and immunity." (PMID 36944688, 2023). "Our analysis revealed that in the breast cancer cell line T47D, HIF-1β binds at the proximal promoter of TRAF6, 178 bp upstream to 366 bp downstream of the transcription start site (TSS) (TSS -178/+366)." (PMID 32344511, 2020). "In accordance to recently published data MDA-MB-435-Hyg human breast cancer cells and M13MDA435-1 and -3 hybrid cells exhibited comparable expression levels of TLR4, TLR9, TRIF, Myd88, and TRAF6." (PMID 27187369, 2016). "miR-146a and miR-146b are highly expressed in the metastatic human breast cancer cell line MDA-MB-231 and negatively regulate NF-κB activity by targeting the 3’ UTRs of IRAK1 and TRAF6." (PMID 25598707, 2014). "In turn, TRAF-6/TAK-1 joins the MAPK pathway and upregulates the subsequent phosphorylation of extracellular signal-regulated kinases (ERK1/2) in all human breast cancer, thus leading to uncontrolled growth, proliferation, and resistance to traditional chemotherapeutic agents such as docetaxel." (PMID 36993955, 2023). "Another report also showed that TRAF6, in a RING-dependent fashion, catalyzed auto-ubiquitination by conjugating with ubc13/Uev1A, activating the AKT pathway, and promoting cell migration in breast cancer." (PMID 35874839, 2022). "Moreover, they also proved that TRAF6-mediated AKT ubiquitination and phosphorylation contributes to oral cancer and breast cancer malignant phenotype in vitro and in vivo." (PMID 32905356, 2020). "To understand whether the downregulation of TLR5 could promote breast cancer metastasis and invasion, we detected EMT markers and its signal pathway, TRAF6 and SOX2." (PMID 31852883, 2019). "Also in breast cancer, miR-146a and miR-146b expression suppressed IRAK1 and TRAF6, which was reported to impair NF-κB activity, resulting in reduced invasion and migration." (PMID 23335942, 2012).
breast carcinoma (continued). "Analysis of data from 212 patients collected from 2 pooled studies showed that high expression of TRAF6, not TRAF4, is associated with poor survival rate in breast cancer patients over a 5-year period (Log Hazard Ratio [HR]:1.01, 95% CI: 1.01, 1.01, P < 0.00001)." (PMID 36944688, 2023). "Therefore, we speculate that inhibiting downstream targets of IL-1 (IRAK1, TRAF6, IKK) has effects on reducing osteoclastic bone resorption, while IL1β inhibition not only reduces osteoclastic bone resorption but also blocks breast cancer metastasis to bone." (PMID 36230739, 2022). "Moreover, ICAM3, CCL16, PDE3A, PRTN3, TRAF6, BCAR1, IL-1α, IL-1β, NFκB1, SOX2 and OCT4 decreases the protein expression as indicated by immunofluorescence staining in the ibuprofen-treated MDA-MB-231 breast cancer cells versus the control." (PMID 32528119, 2020). "TRAF4 modulates canonical signaling in breast cancer cells by ubiquitinating SMURF2 for destruction and mediates non-canonical signaling in a Traf6-independent manner, stabilizing TGFBR at the plasma membrane." (PMID 38313020, 2024). "Based on these findings from pooled studies it is reasonable to conclude that therapeutic targeting of TRAF6, but not TRAF2 and 4, can be of value in the treatment of breast cancer." (PMID 36944688, 2023).